MUC1 (mucin 1, cell surface associated)
Diseases named in the same sentence as MUC1 in open-access papers (continued):
Sharing a sentence is not in itself a finding about the gene and the disease.
gastric cancer (continued). "It is important that we replicate the study about MUC1 polymorphism in Vietnamese population to understand with certainty whether it has different effects on the risk of developing gastric cancer and, in turn, developing a population-specific genetic panel for gastric cancer screening." (PMID 34532288, 2021). "In the other meta-analysis study, with 12,551 cases and 13,436 controls in total from seventeen different case–control studies, suggests different genetic combination (G vs. A; AG vs. AA; GG vs. AA; AG + GG vs. AA) for the MUC1 rs4072037 polymorphism might decrease the risk of gastric cancer." (PMID 32660489, 2020). "Results indicated that the MUC1 5640G > A polymorphism may have protective effect for gastric cancer in the Northern Iran population and could be considered as a potential molecular marker in gastric cancer." (PMID 32660489, 2020). "In gastric cancer tissues, a large variety of oligosaccharides have been detected, including both sialylated and fucosylated core 1 and 2 structures as well as large amount of oligosaccharides on MUC1 with α6-linked sialic acid, (NeuAcα6)GalNAc-ol and Galβ3(NeuAcα6)GalNAc-ol." (PMID 27754373, 2016). "When the MUC1 protein was quantified in blood exosomes of 15 gastric cancer patients and 5 healthy subjects, a significant increase in MUC1 expression was observed in gastric cancer patients." (PMID 40075875, 2025). "MUC1 is well-known oncoprotein that is highly overexpressed in many cancers, including gastric cancer." (PMID 41154387, 2025). "Our findings underscore a significant association between specific genetic polymorphisms, such as those in the genes mucin 1 (MUC1), prostate stem cell antigen (PSCA), tumor necrosis factor-alpha (TNF-α), and an increased risk of developing gastric cancer." (PMID 39355481, 2024). "The activation of Twist1 by Rab31 facilitated through STAT3 stimulation and MUC-1 suppression reveals a novel Rab31/STAT3/MUC-1/Twist1/EMT axis implicated in the drug resistance and metastatic potential of gastric cancer." (PMID 39309860, 2024). "Comparison between MUC1 expression and clinicopathological characteristics of 31 patients with gastric cancer included in the study." (PMID 38324850, 2024). "Identifying genetic markers, such as MUC1, PSCA, and TNF-α, that are significantly associated with gastric cancer susceptibility underscores their potential as diagnostic and prognostic tools." (PMID 39355481, 2024). "The result was accordance with latest meta-analysis by Patel, proving that high MUC1 expression correlated with poorer prognosis and metastases in esophago-gastric carcinoma." (PMID 39886661, 2024). "One of the main glycoproteins of gastric cancer cells is epithelial MUC1 mucin, a well-known oncoprotein, specifically because of its overexpression and altered glycosylation." (PMID 37685842, 2023). "Recently we have demonstrated the anti-tumor potential of tiliroside in AGS gastric cancer cells by affecting MUC1 and some specific glycoforms involved in cancer development." (PMID 37685842, 2023). "hTERT and MUC1- Over expression in gastric cancer as released from neovessels in cancer tissues.Tumor derived mRNA released from tumor tissues detected in circulation in the absence of circulating tumor cells." (PMID 37091783, 2023). "Further studies involving a large number of early gastric cancer patients are needed to confirm the prognostic role of MUC1 in early gastric cancer." (PMID 36831343, 2023). "The proposed therapy utilizing anti-MUC1 with tiliroside seems to be a promising anti-gastric cancer therapy." (PMID 37685842, 2023). "The present study aimed to evaluate the prognostic value of MUC1 expression status in US gastric cancer patients." (PMID 36831343, 2023). "A meta-analysis of 10 retrospective studies from Asia and Europe reported that MUC1 positive gastric cancer patients had a lower 5-year survival rate (hazard ratio 0.27, 95% confidential interval [CI] 0.11–0.66)." (PMID 36831343, 2023).
gastric cancer (continued). "Several ADCs have been developed to specifically target MUC1 for the treatment of gastric cancer, demonstrating significant anti-tumor activity." (PMID 37305567, 2023). "Existing studies have shown that the loss of O-glycans derived from core 1 can lead to dysregulation of MUC1 expression, damage to the gastric mucus layer, and altered gastric acid balance, leading to the occurrence of gastritis and gastric cancer (GC)." (PMID 37894512, 2023). "Our study showed a possible prognostic role in early gastric cancer, and a high level of MUC1 expression by using the composite score of IHC which had more submucosal invasion and lymph node metastasis in early gastric cancer." (PMID 36831343, 2023). "As shown with circulating cell-free hTERT and MUC1 mRNA that can provide a screening tool for the early detection of gastric cancer and its relapse." (PMID 37091783, 2023). "Although this study is the first study evaluating the prognostic roles of MUC1 expression in US gastric cancer, there are several limitations." (PMID 36831343, 2023). "A study investigated the effect of RA on some cancer related factors, viz., collagen, MMP, and TIMP, as components of ECM, and on protein glycosylation and MUC1, O-glycosylated oncoprotein in the gastric cancer CRL-1739 cell line." (PMID 37836581, 2023). "In subgroup analysis, including the early gastric cancer, the MUC1 high expression was related to the higher rate of lymphovascular invasion." (PMID 36831343, 2023). "The results from previous studies and our study results suggest the role of MUC1 as a prognostic marker for gastric cancer." (PMID 36831343, 2023). "In the resected gastric cancer tissues, mucin expression rates were 71.4% for MUC1, 78.6% for MUC2, 75.4% for MUC5AC, and 33.3% for MUC6." (PMID 36831343, 2023). "Recently, we showed also that luteolin decreased expression of MUC1 extracellular domain in CRL-1739 gastric cancer cells." (PMID 35955735, 2022). "In breast and gastric cancers, MUC1 expression plays a role in trastuzumab resistance; anti-MUC1 monoclonal antibody (mAb) overcomes this situation." (PMID 35248049, 2022). "MUC1-Tn-CAR-Vγ9Vδ2 T cells more effectively suppressed tumor growth than Vγ9Vδ2 T cells in a xenograft murine gastric cancer model." (PMID 35747139, 2022). "MUC1-positive gastric cancer cells with sialyl Tn (sTn) antigen exhibit more metastatic potential than MUC1-positive cells alone." (PMID 36497322, 2022). "The strongest pro-apoptotic effect on gastric cancer cells was revealed by combined treatment of PtPz6 and anti-MUC1 (26.8% of apoptotic cells)." (PMID 34206951, 2021). "We checked the effect of the tested compounds in lower doses than IC50 (OM-86II, etoposide, anti-MUC1 antibody, OM-86II + anti-MUC1, etoposide + anti-MUC1) on viability and DNA biosynthesis in gastric cancer cells after 24 and 48 h of incubation." (PMID 34770912, 2021). "There are anti-MUC1 based therapies developed against gastric cancer; some of them are in clinical trials or currently under pre-clinical studies." (PMID 34206951, 2021). "Patients diagnosed with GBM, hepatocellular carcinoma, pancreatic, colorectal, breast or gastric cancer, among others, who express MUC-1, were enrolled for MUC-1-directed CAR-NK cell therapy; however, as of April 2021, the results are still awaited." (PMID 34072732, 2021). "The aim of this study was to characterize the molecular mechanisms of action induced by the monoclonal antibody against MUC1 in combination with the novel diisoquinoline derivative (OM-86II) in human gastric cancer cells." (PMID 34770912, 2021). "Meanwhile 22 variants were identified significantly associated with gastric cancer: 3 (PLCE1 rs2274223, PSCA rs2976392, MUC1 rs4072037) were high and 19 SNPs were intermediate level of summary evidence, respectively." (PMID 34491229, 2021). "Luteolin has been also suggested to support anti-cancer treatment of gastric cancer by effecting MUC1 and sT antigen expression." (PMID 34681197, 2021).
gastric cancer (continued). "Recently, we also demonstrated rosmarinic acid suppressing MUC1 mRNA as well as MUC-1 cytoplasmic tail in gastric cancer cells." (PMID 34681197, 2021). "A number of reports have demonstrated a strong correlation between increased MUC1 expression and worse prognosis in patients with gastric cancer." (PMID 34770912, 2021). "Following 24 h of incubation of gastric cancer cells with monoclonal antibody (5 μg/mL) we observed a significant decrease in MUC1 mRNA expression compared to control." (PMID 34206951, 2021). "The findings of this study proved that the anti-MUC1 antibody contributed to the increased sensitivity of gastric cancer cells to the novel diisoquinoline derivative (OM-86II)." (PMID 34770912, 2021). "Summarizing our results, we suggest the application of two pyrazole-berenil cisPt complexes combined with anti-MUC1 monoclonal antibody as a promising strategy in gastric cancer treatment, more effective than monotherapy." (PMID 34206951, 2021). "Upon treatment with a combination of etoposide or OM-86II with anti-MUC1, we found that they induced autophagy in gastric cancer cells, in comparison with untreated samples." (PMID 34770912, 2021). "RT-PCR and ELISA tests were used to assess the effect of anti-MUC1 mAb action on MUC1 mucin expression in gastric cancer cells." (PMID 34206951, 2021). "The extracellular domain of MUC1 mucin present in gastric cancer cell lysates and culture medium was differently affected by afzelin." (PMID 34681197, 2021). "MUC1 is also a well-established and useful biomarker for the early detection of gastric cancer (GC)." (PMID 34207342, 2021). "The human mucin 1 (MUC1) is a high-molecular-weight membrane-bound glycoprotein overexpressed in most human epithelial cancers, including gastric cancer." (PMID 34206951, 2021). "The analysis revealed that the combination of the anti-MUC1 antibody with OM-86II activated both caspases in AGS gastric cancer cells." (PMID 34770912, 2021). "The aim of this study was avaluating the association of rs4072037G > A polymorphism in MUC1 and rs2294008 C > T in PSCA gene with risk of gastric cancer in northern Iran." (PMID 32660489, 2020). "The use of CAR T-cells targeted against MUC1 is proposed for relapsed or refractory solid tumors like glioma, metastatic colonic adenocarcinoma, and gastric cancer, which exhibit confirmed MUC1 positive status." (PMID 31936611, 2020). "Other factors, such as the upregulation of COX-2 and MUC1 in gastric cancer cells, have been shown to influence the microenvironment by permitting immune evasion, vessel invasion, and metastatic spread." (PMID 31941061, 2020). "Fully glycosylated mucin 1 (MUC1) and hypoglycosylated MUC1 expression intensity and percent of positive tumor cells were examined by immunohistochemistry (IHC) in gastric cancer tissue sections." (PMID 31941061, 2020). "The aim of this study is also evaluating the association between MUC1 gene polymorphism, rs4072037G > A and PSCA gene polymorphism rs2294008C > T with gastric cancer in northern Iran." (PMID 32660489, 2020). "A recent meta-analysis of ten translational studies demonstrate that MUC1 immunohistochemical expression is highly correlated with intestinal histology, vascular invasion, nodal metastasis, and decreased survival in gastric cancer patients." (PMID 31941061, 2020). "For this reason, MUC1 is widely used to monitor the severity of metastases and tumor progression, especially in stomach cancer, with a high level indicating a poor prognosis." (PMID 32560392, 2020). "Elevated MUC1 expression has been observed in gastric cancer patient tumors and is thought to play a critical role in oncogenic signaling." (PMID 31941061, 2020). "A recent study revealed that miR-206 inhibits the progression of gastric cancer by directly targeting MUC1 and reducing its expression in gastric cancer cells." (PMID 33194611, 2020).
gastric cancer (continued). "In gastric cancer patients, a strong correlation was observed to exist between anti-TF IgG and anti-MUC1 IgG antibody levels (P = 0.0001), which speaks about the possibility that these Abs are directed to the TF glycopeptide epitope on MUC1 mucin." (PMID 32280709, 2020). "Numerous epidemiological studies have shown an association between MUC1 VNTR polymorphisms and susceptibility for both H. pylori-induced gastritis and gastric cancer." (PMID 31069176, 2019). "MUC6 and MUC1 are secreted in the stomach and can play an important role in the development of gastric cancer." (PMID 28512631, 2017). "It has been shown that H. pylori regulate the increased expression of MUC1 in gastric cancer cells by CpG hypomethylation and signal transducer and activator of transcription." (PMID 28512631, 2017). "In summary, MUC1 is a prognostic factor in gastric cancer, which acts as a marker of poor outcome in patients with gastric cancer." (PMID 27190429, 2016). "Those subjects with both the risk alleles MUC1 rs9841504 and ZBTB20 rs4072037 had a greater than 3-fold increased risk of gastric cancer." (PMID 27127881, 2016). "Because MUC1 rs4072037 and ZBTB20 rs9841504 increased gastric cancer risk in the whole population, they were used to predict the risk of gastric cancer among the Han Chinese." (PMID 27127881, 2016). "We performed a meta-analysis to evaluate the relationship between MUC1 expression and prognosis of gastric cancer." (PMID 27190429, 2016). "So far several studies have demonstrated that MUC1 positive expression in gastric cancer was determined to be statistically significant, with worse differentiation and higher rate of lymph node metastasis." (PMID 27190429, 2016). "Overexpression of STn in human gastric cancer cell lines also accelerated their ability to form intraperitoneal metastases resulting in shorter survival of mice, credited mostly to MUC1 as the major STn carrier." (PMID 27754373, 2016). "In previous reports, gastric carcinomas were found to contain a higher level of MUC1 mucin expression than normal gastric mucosa." (PMID 27190429, 2016). "The associations of MUC1 rs4072037 T>C and PLCE1 rs2274223 A>G with stomach cancer risk have also been replicated in different ethnicities." (PMID 25658482, 2015). "Several genetic variants including PSCA rs2294008 C>T and rs2976392 G>A, MUC1 rs4072037 T>C, and PLCE1 rs2274223 A>G have shown significant association with stomach cancer risk in the previous genome-wide association studies (GWASs)." (PMID 25658482, 2015). "Logistic regression analysis of associations between the genotypes of PSCA, MUC1, PLCE1 and stomach cancer susceptibility in a Chinese population." (PMID 25658482, 2015). "MUC1 gene amplification due to increased gene copy number has been observed in ovarian, breast, papillary thyroid, and gastric cancers." (PMID 24551091, 2014). "Intriguingly, it was demonstrated that HP upregulates MUC1 expression in gastric cancer cells through STAT3 and CpG hypomethylation." (PMID 24810688, 2014). "The association between co-function of PGC, MUC1 and MUC2 and the occurrence and development of gastric cancer and precancerous disease needs to be clarified in the future." (PMID 23937908, 2013). "The examination of MUC4 and MUC1 expression in the gastric cancers would become a useful marker to predict poor prognostic factors related with vessel invasion, even in the early stage." (PMID 23152882, 2012). "Our previous study also showed that MUC1 expression in gastric cancers, including the early and advanced stages is a poor prognostic factor." (PMID 23152882, 2012). "In our previous study, the rate of high expression of MUC1/DF3 was significantly higher in the advanced gastric cancers than that in the early gastric cancers." (PMID 23152882, 2012). "In conclusion, the expression of MUC4 as well as MUC1 in early gastric cancers is a useful marker to predict poor prognostic factors related with vessel invasion." (PMID 23152882, 2012).
gastric cancer (continued). "Our previous study in gastric cancers, including both early cancers and advanced cancers demonstrated that MUC1 is a useful prognostic factor for poor outcome in the patients." (PMID 23152882, 2012). "Phenotypic studies in cell models other than gastric cancer have suggested that MUC1 influences events such as proliferation, apoptosis, migration, invasion, adhesion and cell-cell aggregation." (PMID 22073229, 2011). "A positive correlation (p = 0.0001) between circulating Thomsen-Friedenreich (TF) IgG and MUC1 IgG abs was found in patients with early stage gastric cancer." (PMID 24212946, 2011). "MUC1 IgG and IgM ab levels were studied in 91 healthy blood donors, 160 patients with chronic gastroduodenal diseases and in 214 patients with gastric cancer and related to H. pylori serologic status." (PMID 24212946, 2011). "We evaluated the net effects of downregulating MUC1 in the MKN45 gastric carcinoma cell line by performing a global analysis of gene expression by oligonucleotide microarrays." (PMID 22073229, 2011). "In the work presented here, we evaluated the effects of MUC1 downregulation on cancer-related properties of MKN45 gastric carcinoma cells." (PMID 22073229, 2011). "In the report presented here we used retrovirus-mediated transfection of short-hairpin RNAs (shRNA) to induce a stable downregulation of MUC1 in the gastric carcinoma- derived cell line MKN45." (PMID 22073229, 2011). "Stable downregulation of MUC1 expression was achieved in MKN45 gastric carcinoma cell line by RNA interference." (PMID 22073229, 2011). "We also showed that the quantification of circulating mRNA such as hTERT and MUC1 using RT–PCR would be useful for the early detection of primary and recurrent gastric cancers." (PMID 20389301, 2010). "The observations that MUC1 plays a role in the progression to gastric cancer highlight the importance of understanding all the aspects of the normal variation of this gene." (PMID 19238635, 2008). "Individuals with small MUC1 genotypes (SS) are at increased odds (4.3; 1.8–10.5) for gastric carcinoma development." (PMID 18000536, 2007). "In gastric cancer, high expression of MUC4 and MUC1 is associated with poor patient prognosis." (PMID 39895782, 2025). "The present study aimed to summarize the role of MUC1 mucin in gastric cancer development." (PMID 41154387, 2025). "The present review summarizes the role of MUC1 in gastric cancer development." (PMID 41154387, 2025). "Moreover, the cell adhesion pathway modulates gastric cancer cell sensitivity to cisplatin by regulating adhesion molecules such as Muc-1, ICAM-1, and VCAM-1." (PMID 40069421, 2025). "The method reported a LOD of 2.15 × 106 particles/μL using MUC1 probe for gastric cancer cell line HGC-27-derived EV sample, as well as validation for other gastric cancer biomarkers (EpCAM, PTK7, PD-L1) for both cell line EV isolates and human plasma specimens." (PMID 41404198, 2025). "Other authors pointed out that MUC1 positivity might be correlated with the invasiveness of gastric carcinoma cells, as demonstrated by experiments revealing that MUC1-positive tumors were associated with synchronous liver metastasis." (PMID 41154387, 2025). "In the previous study, it is not exactly clear that a strong relationship exists between MUC1 rs4072037 polymorphism and gastric cancer." (PMID 38463926, 2024). "CK20 and MUC1 expression levels could be assessed by qRT-PCR from total peripheral blood samples of patients with gastric cancer." (PMID 38324850, 2024). "Among 24 patients with early gastric cancer, the MUC1 expression was found in 10 patients (41.7%)." (PMID 36831343, 2023). "MUC1 is a useful prognostic biomarker for predicting gastric cancer outcomes." (PMID 36831343, 2023). "MUC1 expression is related to invasiveness and metastasis in gastric cancer." (PMID 37529165, 2023).